HIF1A (hypoxia inducible factor 1 subunit alpha)
Diseases named in the same sentence as HIF1A in open-access papers (continued):
Sharing a sentence is not in itself a finding about the gene and the disease.
breast cancer (continued). "We show that JFK deficiency leads to a decrease in HIF-1α-induced glycolysis in breast cancer and sensitizes hypoxic breast cancer cells to ionizing radiation and chemotherapeutic treatment." (PMID 34336836, 2021). "On the contrary, loss of HIF-1α specifically in FSP1+ CAFs was found to accelerate mammary tumor growth and also contribute to decreased tumor vessel density." (PMID 34202979, 2021). "HIF-1α expression is associated with reduced disease-free survival and a poorer response to hormone-based therapy in breast cancer." (PMID 33808542, 2021). "Previous studies have reported mixed associations between HIF-1α expression and breast cancer prognosis." (PMID 34736510, 2021). "Upregulation of HIF1A in BRCA1-deficient fibroblasts has previously been shown to drive breast cancer growth." (PMID 33898308, 2021). "HIF-1α is overexpressed in primary breast cancer, that is associated with over proliferation and poor differentiation." (PMID 33245358, 2020). "HIF-1α is often considered a hallmark for poor prognosis in breast cancer, with patients experiencing shorter distant metastasis- and disease-free survival." (PMID 33266219, 2020). "In various types of cancers, such as melanoma, breast cancer, and colorectal cancer, HIF-1α has been associated with aggressiveness and poor outcomes." (PMID 32847004, 2020). "In a recent study assessing the prognostic value of HIF-1α in 220 patients with stages II–III breast cancer receiving chemotherapy, HIF-1α expression was associated with a worse pathological response." (PMID 33266219, 2020). "Particularly, pathways related to EMT, including the HIF-1α transcription factor network, were strongly associated with migratory breast cancer cells." (PMID 33374849, 2020). "This compound induces angiogenesis, induces HIF1α, which is associated with cancer cell growth and poor prognosis, and stimulates folate uptake by breast cancer cells." (PMID 31936350, 2020). "Upregulation of transcription factor HIF1-α, the most crucial component of the hypoxia pathway, has been frequently observed in breast cancer and is associated with poor prognosis in patients." (PMID 33182737, 2020). "In this regard, it is worth mentioning that an elevated expression of HIF-1α has been associated with the aggressiveness of breast cancer and poor clinical outcomes." (PMID 32778144, 2020). "Our results indicate that in hypoxic MCF-7 breast cancer cells, HT decreases the expression of HIF-1α, an effect probably linked to its antioxidant action and to the down-regulation of the PI3K/Akt/mTOR pathway." (PMID 32286485, 2020). "It is well known that intratumoral hypoxia can drive breast cancer neoangiogenesis, and now it has also been associated with an enhancement of exosome release from breast cancer cells in a HIF-1α-dependent manner." (PMID 32764376, 2020). "HIF1A functions as a tumor promoter in cancer-associated fibroblasts, and as a tumor suppressor in breast cancer cells, also it is already a vaccine target in triple-negative breast cancer." (PMID 32293263, 2020). "Transcripts encoding canonical HIF1A target genes are also increased in brain tumors versus mammary tumors." (PMID 33298946, 2020). "Hypoxia can cause enrichment of breast cancer stem cells (BCSCs) mediated by hypoxia inducible factor 1 alpha (HIF1α)." (PMID 33255471, 2020). "HIF1-α has been implicated in breast cancer tumor growth and metastasis, and in tumor aggressiveness associated with a poor prognosis." (PMID 33153193, 2020). "HIF-1α over-expression is associated with advanced cancer progression and poor clinical outcomes in breast cancer patients." (PMID 31455352, 2019).
breast cancer (continued). "Additional researchers have implicated EGFR in antiestrogen resistance, and HIF-1α seem to covariate with EGFR-expression in breast cancer." (PMID 31821370, 2019). "Nuclear HIF-1α has been identified to be largely associated with EMT in breast cancer metastasis, and can also be regulated by the interaction between E-cadherin and Hippo pathway factors." (PMID 30961610, 2019). "The miRNA-mRNA network shows that significantly deregulated miRNAs in the FS and FSO groups target genes involved in the MG development (red circles) and/or associated with breast cancer (blue circles), including Egfr, Igf-1, Igf-1R, Hif1a, Ets1, and pgr." (PMID 31689992, 2019). "Whilst HIF-1α expression has been consistently associated with disease progression and worse prognosis in breast cancer, the prognostic implications of HIF-2α expression have remained unclear." (PMID 30670058, 2019). "Previous study suggested that circDENND4C is a HIF1A-associated circRNA, which is highly expressed in hypoxia condition and promotes cell proliferation at 4 days in breast cancer." (PMID 31488193, 2019). "HIF-1α expression in breast cancer is associated with more aggressive disease as HIF target genes can promote cancer cell survival in the hypoxic tumour microenvironment by regulating processes such as glycolysis, angiogenesis and metastasis." (PMID 30670058, 2019). "Hypoxia and HIF-1α were recognized to be responsible for enhanced osteolytic bone metastases in MDA-MB-231 breast cancer cell lines, causing a poor prognoses and an increased patient mortality." (PMID 31903166, 2019). "Several lines of evidence have suggested that the IGF-IR/IR signaling is implicated in the activation of the HIF-1α pathway in breast cancer." (PMID 29996493, 2018). "Clinical studies have shown that HIF-1α expression is associated with an aggressive phenotype of breast cancer, i.e., large tumor size, high grade, high proliferation rate, and lymph node metastasis." (PMID 29342868, 2018). "In fact, its overexpression is implicated in the increase of invasive phenotype in breast cancer cells, in synergy with exposure to the hypoxic tumor microenvironment and with HIF-1α expression." (PMID 29716631, 2018). "Suppression of VASP is associated with TNF-α and HIF-1α induced inhibition of breast cancer cell adhesion and proliferation.Downregulation of VASP expression inhibits breast cancer cell migration and invasion." (PMID 30271395, 2018). "The levels of HIF-1α in the mitochondrial fraction of BRCA1 mutated breast cancer cells is significantly increased compared to sporadic models." (PMID 29584711, 2018). "An increased HIF1-α level in primary malignant neoplasias is tightly associated with the density of the surrounding tumour lymphatic vessels and with breast cancer patient mortality." (PMID 29362402, 2018). "Intratumoral hypoxia and elevated levels of HIF-1α have been correlated with poor prognosis in breast cancer patients, and is linked to an increase in tumor size, lymph node metastasis, tumor stage, and histological grade." (PMID 29628507, 2018). "High levels of hypoxia-inducible factor-1α (HIF-1α) are associated with advanced cancer progression and poor clinical outcomes in breast cancer patients." (PMID 30367042, 2018). "While several studies showed an association between HIF-1α overexpression and poor prognosis in breast cancer, a conclusive view on the role of PHD2 in cancer has not been reached." (PMID 28038470, 2017). "The upregulated levels of HIF-1α in breast cancer are associated with high tumor grade, high proliferating microvessel density, increased rate of metastasis, as well as with a decreased breast cancer-specific survival." (PMID 28038470, 2017). "Hypoxia-inducible factor 1-alpha (HIF1A) is a key regulator of the hypoxia response and has been linked to breast cancer progression." (PMID 28077088, 2017).
breast cancer (continued). "Our present findings indicate that this is also the case in African breast cancer since we found strong associations of HIF-1α expression with features of aggressive tumors." (PMID 26760782, 2016). "HIF1A activation under normal oxygen tension has been linked to anoikis resistance of breast cancer cells driven by ERBB2 oncogene, and circulating breast tumor cells from patients with metastatic breast cancer." (PMID 27495308, 2016). "In experimental studies, HIF-1α was up-regulated in CSC-like cells that showed elevated ALDH1 expression, and ALDH1 was found to be associated with HIF-1α in locally advanced breast cancer." (PMID 26760782, 2016). "It is noteworthy that the increased HIF-1α expression has been correlated with a worse prognosis of breast cancer patients, while CREB increased the risk of metastases in HER-2/neu+ breast cancer." (PMID 27409833, 2016). "We have recently found that MLN4924 effectively induced autophagy in breast cancer cell lines via causing accumulation of HIF1α and DEPTOR to inactivate mTORC121." (PMID 27063292, 2016). "Increased levels of HIF-1α protein in the primary tumor biopsy has been shown to be associated with increased mortality range in several cancers, including breast cancer." (PMID 27540529, 2016). "We identified a function of NQO1 in which HIF-1α stability was markedly enhanced under hypoxia following ectopic introduction of NQO1 into NQO1-deficient MDA-MB-231 breast cancer cells." (PMID 27966538, 2016). "HIF1α and HIF2α are implicated in therapeutic resistance in breast cancer, and HIF2α influences EGFR translation at hypoxia." (PMID 26849233, 2016). "In breast cancer, HIF-1α is associated with high histological grade, lymph node metastasis, large tumor size, high proliferation rate, negativity of HR, HER2 positivity as well as shorter disease-free and OS." (PMID 26512778, 2015). "The aim of this current study was to examine the association of endocrine resistance in human breast cancer with hypoxia and its major regulator, HIF-1α, in vivo." (PMID 25929338, 2015). "In clinical breast cancer tissues, we further demonstrate that miR-373 is positively associated with HIF1α and TWIST, and negatively associated with TXNIP." (PMID 26196741, 2015). "Hypoxia-inducible factor 1α (HIF-1α) expression is a hallmark of intratumoral hypoxia that is associated with breast cancer metastasis and patient mortality." (PMID 26059435, 2015). "In this study, we demonstrate that tamoxifen-resistant breast cancer cells express higher levels of HIF-1α than parental breast cancer cells and it is closely associated with elevated aerobic glycolysis." (PMID 26158266, 2015). "Taken together, the 1772 C > T of HIF-1α gene is a potential biomarker for breast cancer susceptibility." (PMID 25302049, 2014). "Intratumoral hypoxia induces the expression of HIF-1α, which is associated with increased risk of metastasis, relapse, and mortality in multiple clinical studies involving thousands of breast cancer patients." (PMID 25587023, 2014). "This meta-analysis demonstrates that both the C1772T and G1790A polymorphisms in the HIF-1α gene likely contribute to increased cancer susceptibility, especially in the Asian population and in breast cancer, lung cancer, pancreatic cancer and oral cancer." (PMID 25496056, 2014). "In breast cancer, HIF-1α expression is associated with high-grade tumors, loss of estrogen receptor (ER), increased proliferation levels, decreased disease-free and overall patient survival and also with chemo- and radiotherapy resistance." (PMID 25269858, 2014). "In this study, we focused on the relationship between SNP 1772 C > T (rs11549465) of HIF-1α gene and its breast cancer risk, as well as its correlation with HIF-1α expression and tumor angiogenesis." (PMID 25302049, 2014). "We found that 1772 T allele of HIF-1α gene was associated with increased breast cancer risk (adjusted OR = 14.51; 95% CI: 6.74-31.24)." (PMID 25302049, 2014).
breast cancer (continued). "Results from the present study show that the CoCl2-induced hypoxic response in +SA mammary tumor cells caused a large increase in Akt/mTOR signaling proteins associated with promoting HIF-1α expression, and compound 44 blocked this response." (PMID 25140303, 2014). "We found that T allele of the SNP 1772 C > T (P582S) of HIF-1α gene was significantly higher in 96 breast cancer patients than in 120 controls." (PMID 25302049, 2014). "Meta-analysis from 34 case–control studies also reported that SNP 1772 C > T (P582S) of HIF-1α gene is significantly associated with breast cancer risk in many countries." (PMID 25302049, 2014). "Overexpression of HIF-1α in breast cancer is associated with increased patient mortality and HIF target genes play critical roles in angiogenesis, migration, invasion, and metastasis to lymph nodes, lungs, and bone." (PMID 25587023, 2014). "The purpose of this study is to investigate the association between SNP 1772 C > T of the HIF-1α gene in breast cancer patients and healthy control subjects." (PMID 25302049, 2014). "We demonstrated an association between the expression of P-cadherin and HIF-1α in breast carcinomas." (PMID 25269858, 2014). "The dn HIF-1α-induced inhibition of HIF-1α has been reported in a number of types of cancer, including malignant gliomas, gastric cancer and breast carcinoma, however, the underlying mechanism has yet to be elucidated." (PMID 25120692, 2014). "It is known that hypoxia induces BRCA1 downregulation and that BRCA1-mutated breast carcinomas, which are enriched in HIF-1α expression, present aberrant expression of P-cadherin." (PMID 25269858, 2014). "There is a significant increase in HIF-1α positive ASCs in breast cancer patients compared to cancer-free women, and a positive association between HIF-1α and aromatase expression." (PMID 23566437, 2013). "Many breast cancers are associated with heterogeneously distributed hypoxic tissue areas within the tumor mass and hypoxia inducible factor-1α (HIF-1α) is found to be a key mediator of hypoxia-mediated tumor responses." (PMID 23566437, 2013). "Our findings of HIF-1α in tumor-associated breast stroma implicate its potential as a therapeutic target in obesity-related, postmenopausal breast cancer." (PMID 23566437, 2013). "Recent studies have revealed that BRCA1 and BRCA2 germline mutation-related breast cancers show frequent overexpression of hypoxia inducible factor-1α (HIF-1α), the key regulator of the hypoxia response." (PMID 23409121, 2013). "VEGF overexpression and the activation of HIF-1α and NFκB pathways in breast cancer are strongly linked to rapid growth of tumors and worse prognosis." (PMID 23638734, 2013). "HIF-1α is a marker for hypoxia and in breast cancer it has been linked to aggressive malignant behavior." (PMID 23673510, 2013). "In this matter, an increased expression level of HIF-1α in primary breast tumour and metastases has been associated with enhanced rates of metastases at distant sites and decreased survival of breast cancer patients." (PMID 23301832, 2013). "In an animal model of breast cancer bone metastases, inhibition of HIF-1α or TGF-β by either knock down or DNTβRII causes significant reduction in metastases formation with no additive effect when blocked simultaneously." (PMID 24558636, 2013). "A pronounced expression of HIF-1α is linked to an increased risk of death at early stages of various types of malignant tumours, including carcinomas of uterine cervix, esophageal, mammary carcinoma and cerebral oligodendroglioma." (PMID 24153191, 2013). "Association of HIF-1α expression with unfavourable prognosis in patients with breast cancer has been demonstrated by previous studies." (PMID 22424533, 2012). "The impact of HIF-1α alternative splice variant expression on breast cancer prognosis in terms of metastasis risk is not well known." (PMID 20624301, 2010).
breast cancer (continued). "The aim of this study was to analyse HIF-1α splice variant expression in human breast cancer and to evaluate its clinical relevance in terms of prognosis." (PMID 20624301, 2010). "Tissue hypoxia leads to an adaptive response regulated via hypoxia inducible factor-1 (consisting of HIF-1α and HIF-1β), and raised HIF-1α levels have been associated with reduced survival, chemotherapy failure, relapse and risk of metastases in breast cancer." (PMID 20932344, 2010). "In breast cancers HIF-1α splice variant levels were compared to clinicopathological parameters including tumour microvessel density and metastasis-free survival." (PMID 20624301, 2010). "This month in BMC Medicine, Dales and coworkers report on the expression of hypoxia-inducible factor 1α (HIF-1α) splice variants in human breast cancer." (PMID 20624302, 2010). "Levels of each HIF-1α variant mRNA were determined in tumour samples from 53 patients with breast cancer and were compared with lymph node status, tumour size, tumour grade, peritumoural vascular invasion, OR and PgR status." (PMID 20624301, 2010). "Bcl-6, a homolog of the up-regulated Bazf gene, has been found to be up-regulated in breast cancer and associated with higher HIF-1α levels." (PMID 20657781, 2010). "The frequency of the HIF-1α 1790 A allele was very low and only two studies were included in the breast cancer subgroup." (PMID 20035632, 2009). "The pooled effects for allelic frequency comparison and dominant model comparison suggested a significant association between the HIF-1α 1790 G/A polymorphism and a decreased breast cancer risk." (PMID 20035632, 2009). "Our meta-analysis suggests that the HIF-1α 1772 C/T polymorphism is significantly associated with higher cancer risk, and 1790 G/A polymorphism is significantly associated with decreased breast cancer risk." (PMID 20035632, 2009). "First, the frequency of the HIF-1α 1790 A allele was very low and only two studies were included in the breast cancer subgroup." (PMID 20035632, 2009). "Our meta-analysis suggests that the HIF-1α 1772 C/T polymorphism is significantly associated with higher cancer risk, and the 1790 G/A polymorphism is significantly associated with decreased breast cancer risk." (PMID 20035632, 2009). "In a study in breast cancer, peri-necrotic HIF-1α was associated with the expression of CA9 and Glut-1 and a poor prognosis." (PMID 17179985, 2007). "DEC1 is induced by hypoxia through a HRE, and in our study we have demonstrated a significant association with HIF-1α and the hypoxia-induced gene angiogenin, supporting its induction by this microenvironmental stress in breast cancer." (PMID 15328513, 2004). "Loss of CLDN6 may lead to increased HIF-1α-driven breast cancer metastasis in a SUMOylation-dependent manner." (PMID 40508219, 2025). "Therefore, this review focuses on the structure and function of HIF-1α, its role in advancing breast cancer, and strategies to combat HIF-1α-dependent drug resistance, underlining its therapeutic potential." (PMID 38799423, 2024). "Hypoxia-mediated induction of HIF-1α has been strongly linked to breast cancers developing therapy resistance, which may present an interesting opportunity to explore therapeutics to target the HIF axis in endocrine-resistant disease." (PMID 39282472, 2024). "Therefore, we evaluated the impact of beclin 1-mediated autophagy on reduced drug sensitivity in breast cancer chemoresistance attributed to the reduction in miR-30a caused by HIF-1α through the loss of miR-622." (PMID 38339408, 2024). "As is well known, HIF1α plays a crucial role in regulating the adaptive responses of tumor cells to hypoxic conditions, its high expression has been observed in various types of tumors including breast cancer, and is associated with a poor prognosis." (PMID 39532855, 2024). "In addition to its metabolic effects, HIF-1α stabilization is associated with increased chemoresistance in breast cancer cells." (PMID 39408832, 2024).